RNU1-115P (RNA, U1 small nuclear 115, pseudogene)
Gene: Small nuclear RNA gene on chromosome X (133,238,657 to 133,238,816, reverse strand). Ensembl gene ENSG00000202199.
Homologues: Orthologues: chimpanzee U1 (99% identical), macaque U1 (94% identical), rabbit U1 (80% identical), pig U1 (79% identical), rabbit U1 (79% identical), rat U1 (78% identical), mouse Gm22866 (77% identical), rabbit U1 (73% identical), guinea pig U1 (72% identical), dog U1 (69% identical), mouse Gm56267 (45% identical). Paralogues in human: RNU1-1 (86% identical), RNU1-2 (86% identical), RNU1-27P (86% identical), RNU1-28P (86% identical), RNU1-3 (86% identical), RNU1-4 (86% identical), RNVU1-18 (86% identical), RNVU1-29 (86% identical), RNVU1-31 (86% identical), U1 (86% identical), RNU1-39P (86% identical), RNU1-89P (86% identical), and 134 more.